CCL19 (C-C motif chemokine ligand 19)
Diseases named in the same sentence as CCL19 in open-access papers (continued):
Sharing a sentence is not in itself a finding about the gene and the disease.
pulmonary diseases (1 paper, 2022). "It was found that smoking may correlate with elevated CCR7 mRNA expression level, that CCR7 plays a major role in modulating inflammatory responses in airways in pulmonary diseases, and that cigarette smoking upregulates CCR7, CCL19, and CCL21 mRNA expression levels in lymph nodes of wild-type mice." (PMID 35160116, 2022).
pulmonary sarcoidosis (1 paper, 2015). Sarcoidosis affecting the lung parenchyma. "Our analysis therefore nominated CCL2 and CCL5, both chemoattractants of mononuclear and mast cells, as well as CCL19, a chemokine implicated in T-lymphocyte recruitment, as key candidate chemokines associated with prognosis of pulmonary sarcoidosis." (PMID 26696750, 2015).
pulmonary tuberculosis (1 paper, 2021). A bacterial infection that affects the lungs and is caused by Mycobacterium tuberculosis. "CCR7 ligation by CCL19 and CCL21 is vital for the positioning of T cells and dendritic cells of secondary lymphoid tissues, and CCR7-deficient mice, which are deficient in CCL19 and CCL21 signaling, are fully capable to control pulmonary tuberculosis." (PMID 33686954, 2021).
purpura (1 paper, 2024). A small blood vessel hemorrhage into the skin and/or mucous membranes. "CCL19 (p-adj = 3.68 × 10− 2), osteopontin (p-adj = 3.68 × 10− 2) and ANGPTL4 (4.47 × 10− 2) were significantly higher in IgAV patients with necrotic purpura." (PMID 38610060, 2024). "CCL19 serum concentration was significantly increased in IgAV patients with necrotic compared to nonnecrotic purpura, suggesting that chemotactic activity might contribute to a more severe skin involvement." (PMID 38610060, 2024).
renal cell carcinoma (1 paper, 2023). "For example, previous study described a 12-chemokine gene signature, and identified CCL19 as key chemokine for the maturation heterogeneity of tertiary lymphoid structures (TLS) in renal cell carcinoma, reflecting different TME immunological status and prognosis of cancers." (PMID 37944262, 2023).
rickettsiae infection (1 paper, 2014). "Based on their role in concerting immunological and inflammatory responses, we hypothesized that CCL19 and CCL21 may play a pathogenic role in rickettsiae infection." (PMID 24507453, 2014). "Based on their essential role in concerting immunological and inflammatory responses we hypothesized that the homeostatic chemokines CCL19 and CCL21 may play a pathogenic role in rickettsiae infection." (PMID 24507453, 2014).
sarcoma (1 paper, 2024). A usually aggressive malignant neoplasm of the soft tissue or bone. "SQLE expression was negatively correlated with the expression of chemokines (CCL19 and CX3CL1) and chemokine receptors (CCR2 and CCR7) in sarcoma." (PMID 38335381, 2024).
skin inflammatory diseases (1 paper, 2024). "CCL19 is a chemokine typically expressed in thymus and lymph nodes to regulate immune cell trafficking, but it does not have an established role in skin inflammatory diseases." (PMID 39190494, 2024).
squamous cell carcinoma (1 paper, 2014). A carcinoma arising from squamous epithelial cells. "This idea is further supported by the observation of a significantly higher rate of tumor growth in wild-type BALB/c mice compared to plt mice, which lack CCL19 and CCL21, implanted with a syngeneic squamous cell carcinoma cell line." (PMID 24700353, 2014).
T cell lymphoma (1 paper, 2016). "CCL19 and CCL21 have been reported to have the same efficacy and potency in G protein activation (in H9 T cell lymphoma cells) and Ca2+ flux (in L1.2 cells, a murine pre-B cell line)." (PMID 28018341, 2016).
thyroid cancer (1 paper, 2025). "Additionally, there was a notable association between levels of FGF19, IL2RB, TNFRSF9, S100-A12, FLT3LG, and CCL19 and a decreased risk of thyroid cancer." (PMID 40072746, 2025). "Our MR analysis suggests that genetically predicted circulating CCL19 has a protective role against thyroid cancer." (PMID 40072746, 2025). "Consequently, the specific effects of CCL19 on thyroid cancer should be examined in the specific characteristics and interactions within the thyroid cancer tumor microenvironment." (PMID 40072746, 2025).
Tinnitus (1 paper, 2025). Tinnitus is an auditory perception that can be described as the experience of sound, in the ear or in the head, in the absence of external acoustic stimulation. "This Mendelian randomization study reveals that elevated CCL19 increases tinnitus risk via pantothenate‐mediated inflammation, implicating the CCL19‐pantothenate‐TLR4/NF‐κB axis as a causal pathway." (PMID 40898658, 2025). "This first MR‐based evidence establishes CCL19‐pantothenate axis dysfunction as a causal driver of tinnitus, prioritizing these biomarkers for early detection." (PMID 40898658, 2025). "CCL19 had statistically significant differences and was further identified as a risk factor for tinnitus according to the OR value (OR = 1.071; 95% CI, 1.005–1.141; p = 0.032)." (PMID 40898658, 2025). "CCL19 was positively correlated with tinnitus risk (OR = 1.071, 95% CI, 1.005–1.141, p = 0.032), suggesting that CCL19 may be a risk factor for tinnitus." (PMID 40898658, 2025). "In other words, CCL19 may increase the risk of tinnitus by increasing the level of pantothenate." (PMID 40898658, 2025). "MR analysis showed that Chemokine (C‐C motif) Ligand 19 (CCL19) (OR = 1.071; 95% CI, 1.006–1.141; p = 0.032) was positively correlated with tinnitus." (PMID 40898658, 2025). "Integrating multi‐omics data and constructing the regulatory network of CCL19 and pantothenic acid in tinnitus will help to understand their functions and mechanisms of action more comprehensively." (PMID 40898658, 2025). "This not only suggests a facilitative role of CCL19 in the pathogenesis of tinnitus but also points to pantothenic acid as a possible key downstream mediator of the pro‐tinnitus effect of CCL19." (PMID 40898658, 2025). "This novel finding not only reveals the importance of CCL19 in the pathological mechanism of tinnitus but also provides a theoretical basis for using CCL19 as a potential specific target for treating and preventing tinnitus." (PMID 40898658, 2025). "Based on this, future studies can deeply analyze the molecular mechanism of related metabolites, construct a molecular network model of tinnitus, and develop CCL19 and pantothenic acid‐based intervention strategies to improve the prevention and treatment of tinnitus." (PMID 40898658, 2025). "The role of CCL19 in tinnitus has yet to be reported in the literature." (PMID 40898658, 2025). "Among the metabolites, pantothenate (OR = 1.047; 95% CI, 1.012–1.082; p = 0.007) may play a critical mediating role in CCL19‐induced tinnitus." (PMID 40898658, 2025). "Further analysis showed that CCL19 may indirectly promote the development of tinnitus by increasing the level of pantothenic acid." (PMID 40898658, 2025). "Taken together with the positive association between pantothenate levels and tinnitus risk found in previous studies (OR = 1.047; 95% CI, 1.012–1.082, p = 0.007), this new finding points to a possible mediating role of pantothenate in the effect of CCL19 on tinnitus." (PMID 40898658, 2025). "This suggests that CCL19 may promote tinnitus by activating these signaling pathways, thereby increasing pantothenate levels." (PMID 40898658, 2025). "Further, by protein–protein interaction network and functional enrichment analysis, we found that CCL19 might promote tinnitus by exacerbating oxidative stress, inflammatory response, and inflammatory signaling pathways involving pantothenate‐related genes." (PMID 40898658, 2025). "CCL19 may directly regulate genes involved in pantothenic acid metabolism and promote tinnitus by activating downstream signaling pathways." (PMID 40898658, 2025). "The results of previous MR analyses suggest that CCL19 may promote the development and progression of tinnitus by increasing pantothenate levels." (PMID 40898658, 2025). "This indicates that metabolites may serve an indispensable mediating function solely within the CCL19 pathway and that their involvement in the pathogenesis of other inflammatory factors in tinnitus is constrained." (PMID 40898658, 2025).
Tinnitus (continued). "As a proinflammatory factor, CCL19 may enhance oxidative stress and inflammatory responses by activating these genes, promoting tinnitus." (PMID 40898658, 2025). "Thus, CCL19 may increase pantothenic acid levels and activate its downstream pro‐tinnitus signaling pathway." (PMID 40898658, 2025). "This suggests that CCL19 may promote the occurrence and development of tinnitus by promoting oxidative stress and inflammatory responses involving pantothenate‐related genes and influencing the response process to inflammatory factors, thereby remodeling the related auditory nerve circuit." (PMID 40898658, 2025). "The results showed that CCL19 significantly increased the level of pantothenate (OR = 1.071; 95% CI, 1.006–1.141; p = 0.032), which was consistent with the increased risk of tinnitus, suggesting that pantothenate may play an essential role in CCL19‐induced tinnitus." (PMID 40898658, 2025).
tuberculosis (1 paper, 2022). A chronic, recurrent infection caused by the bacterium Mycobacterium tuberculosis. "CCL19 may become a new target for tuberculosis treatment, and its diagnostic value has been confirmed by our research." (PMID 35345666, 2022). "According to the results of ROC analysis, CCL19 may become a biomarker for the diagnosis of tuberculosis." (PMID 35345666, 2022).
type 1 diabetes (1 paper, 2021). "A similar behavior was found in a type 1 diabetes model where the monocytes were less strongly attracted by MCP-1 (CCL2) and MIP-1α (CCL3) but stronger to MIP-3β (CCL19)." (PMID 34502120, 2021).
unstable angina (1 paper, 2012). "Interestingly, increased levels of CCL19 and CCL21 in atherosclerotic plaques have been found in stable and unstable angina." (PMID 23077561, 2012).
urothelial carcinoma (1 paper, 2025). A malignant neoplasm derived from the transitional epithelium of the urinary tract (urinary bladder, ureter, urethra, or renal pelvis). "To further investigate the therapeutic potential of CXCL13, CCL19, and IL32 for urothelial carcinoma, we performed Cox survival analyses in eight distinct cohorts." (PMID 39739621, 2025).
viral meningitis (1 paper, 2019). Inflammation of the membranes surrounding the brain and spinal cord due to a viral infection. "Both, bacterial and viral meningitis additionally displayed significantly elevated concentrations of the cytokines CCL1, CCL19, CCL20, CXCL2, CXCL6, IFNγ, and IL16." (PMID 31727097, 2019).
vitamin D (1 paper, 2013). "Increased expression of CCL19 mRNA was observed in the CD11c+ cells from male vitamin D-deficient mice, when compared to their vitamin D-replete counterparts, while vitamin D deficiency down-regulated the expression of mRNAs of CCL11, CCL19, CCL20 and CXCL1 in CD11c+ cells from female mice." (PMID 23826346, 2013).
vitiligo (1 paper, 2024). Generalized well circumscribed patches of leukoderma that are generally distributed over symmetric body locations and is due to autoimmune destruction of melanocytes. "A microarray study examining pools of cDNA from growing feathers of Smyth chickens collected before and at disease onset found evidence of both humoral (Ig-J chain, CXCL13) and cell-mediated (CCL19, GZMA, IL21R) immune activities prior to vitiligo onset." (PMID 38720888, 2024). "Highly significant changes in the expression of recruitment and homing-related genes CCL19, CCR7 and CXCL8 were found in growing feathers of vitiligo-expressing Smyth chickens (P < 0.0001)." (PMID 38720888, 2024). "Here, we document a sequence of immunologically significant events, including characteristic rises in infiltrating B and αβ T cells as well as evidence of active leukocyte recruitment and cell-mediated immune activities (CCL19, IFNG, GZMA) leading up to visual vitiligo onset." (PMID 38720888, 2024).
ZIKV infection (1 paper, 2022). "The downregulation of inflammatory genes CCL18, CCL19, CXCL6, CXCL9, IL6R, IL11, IL24, and Integrin Subunit Beta 3 (ITGB3) with ZIKV infection may reflect placental immune tolerance." (PMID 35304593, 2022).
tumor (310 papers, 2006 to 2026). "Those anti-tumor effects are mainly caused by the pathways of B cells, such as CCL19, -21/CCR7 axis and CXCL13/CXCR5 axis." (PMID 40158161, 2025). "The results indicate that CCL19 is not only closely linked to immune cell infiltration in the tumor microenvironment, particularly in the recruitment of T cells and dendritic cells, but also strongly correlated with lymphangiogenesis." (PMID 40895068, 2025). "Specifically, in cluster 1, we found that the chemokine CCL19 produced by fibroblasts and markers of tumor-associated fibroblasts such as SFRP1, PI16, and ADH1B were significantly expressed." (PMID 40538442, 2025). "On the other hand, research has indicated that CCL19 secreted by cancer-associated fibroblasts (CAFs) promotes CD8+ T cell infiltration into the tumor microenvironment (TME) in lung cancer, leading to tumor growth inhibition." (PMID 38300311, 2024). "One way to utilize anti-tumor chemokines is by increasing the concentration of CCL19, which is associated with antigen-presenting." (PMID 38475811, 2024). "Another study confirmed that pretreating the tumor with a recombinant adeno-associated virus bearing the CCL19 gene (AAV-CCL19) increased the infiltration of GPC3 CAR T cells into the tumor tissue and significantly extended the survival of mice." (PMID 38473878, 2024). "To further explore the relationship between the CCR7/CCL19 chemokine axis prognostic risk model and immunity, we explored the relationship between riskScores and immune infiltrating cells, tumor microenvironment, ssGSEA scores and HLA genes." (PMID 37864213, 2023). "This study aimed to analyze transcription expression, genomic alteration, association with tumor immune microenvironment of CCL19 expression and its prediction value for prognosis and responses to immunotherapy for patients with cancers." (PMID 37944262, 2023). "In lung cancer, a CCL19-producing population of fibroblasts was associated with enhanced anti-tumour T cell responses and decreased tumour growth." (PMID 36480035, 2023). "In conclusion, our findings support the notion that elevated CCL19 expression is linked to favorable outcomes and enhanced anti-tumor immunity, characterized by increased CD8+ T cell and M1 macrophage presence." (PMID 37944262, 2023). "Changes in the level of CCL19/CCR7 mRNA expression in tumor tissue can be considered as a diagnostic marker for NSCLC patients." (PMID 35160116, 2022). "It was found that all variants had a similar anti-tumour activity, although the oHSV2-GM-CSF and oHSV2-IL-7 -CCL19 were slightly more efficient than the other three viruses (oHSV2-IL-12, oHSV2-IL-15, oHSV2-PD-1v)." (PMID 36140243, 2022). "a recombinant adeno-associated virus 2 (AAV2) subtype carrying the CCL19 gene was used to pretreat the tumor before the Glypican-3 (GPC3) CAR-T treatment." (PMID 34527749, 2021). "In the analysis of immune cell infiltration in tumor microenvironment, the expression of CCL19 was associated with macrophages M1 and monocyte." (PMID 34544443, 2021). "The results indicated that AAV-CCL19 effectively infected tumor cells and caused continuous expression of CCL19." (PMID 34527749, 2021). "In multivariate analysis only tumor size, node involvement and infiltration by CCL19-expressing DC were significantly associated with poorer RFS (p values of 0.017, 0.001 and 0.047 respectively)." (PMID 21624121, 2011). "We also found that tumor infiltration by CCL19-expressing DC was associated with shorter relapse-free survival in both univariate and multivariate analysis." (PMID 21624121, 2011). "Tumor infiltration by CCL19/MIP3β-expressing DC was associated with both higher tumor grade (p = 0.040) and HER2 overexpression (p = 0.015)." (PMID 21624121, 2011). "Elevated CCL19 levels, when associated with activated B cells, may facilitate their recruitment to the tumor microenvironment." (PMID 40895068, 2025).